PLOD2 (procollagen-lysine,2-oxoglutarate 5-dioxygenase 2)
Diseases named in the same sentence as PLOD2 in open-access papers (continued):
Sharing a sentence is not in itself a finding about the gene and the disease.
cancer (continued). "Therefore, PLOD2 may contribute to cancer progression by modulating collagen cross-linking and maturation." (PMID 32284742, 2020). "Therefore, PLOD2 is thought to be a novel prognostic factor in several types of cancer." (PMID 31455288, 2019). "Importantly, abnormal PLOD2 expression has been observed in many types of cancer." (PMID 31455288, 2019). "However, function of secreted PLOD2 in cancer development and progression remains to be determined." (PMID 30003082, 2018). "For instance, PLOD2’s role in collagen cross-linking and ECM stiffening has direct implications for the biomechanical environment favoring cancer cell dissemination." (PMID 40943497, 2025). "PLOD2 induces EMT and enhances cancer cell stemness and colonization by upregulating cytoplasmic succinate levels." (PMID 39125923, 2024). "We analyzed the mRNA expressions of PLOD1, PLOD2, and PLOD3 in various cancer and normal tissues using Oncomine database." (PMID 39068670, 2024). "Emerging evidence indicates that upregulation of PLOD2 affects ECM fiber arrangement, cell adherent ability and directional migration ability in several kinds of cancers, including RCC." (PMID 38233403, 2024). "In cancer, P4H2A and PLOD2 are vital for collagen posttranslational modification and folding leading to the formation of a stiff ECM and induction of EMT and cancer stem cell marker gene expression, resulting in metastatic dissemination." (PMID 36826019, 2023). "Thus, PLOD2 may play an important role in cancer progression and metastasis." (PMID 36276118, 2022). "Therefore, PLOD2 may play an important role in cancer metastasis." (PMID 36276118, 2022). "Accumulating evidence has implicated members of the procollagen-lysine, 2-oxoglutarate 5-dioxygenase (PLOD) gene family, PLOD1, PLOD2, and PLOD3, in cancer progression and metastasis." (PMID 35265665, 2021). "Subgroup-specific genes with strong effects on overall survival and high MIFs in the proposed weighted model involve the following cancer-related genes: ADH1C, BMP5, LCN2 and PLOD2 in GSE31210, CST1 in GSE37745, as well as AREG and COL4A3 in GSE29013." (PMID 34876106, 2021). "Therefore, PLOD2 may affect cancer progression by modulating collagen cross-linking and maturation." (PMID 33692828, 2021). "In this study, we identified PLOD2 among the genes that are induced, and which are required for the properties conferred by L1 overexpression in CRC cells during cancer progression." (PMID 33805564, 2021). "We focused on a clinically important gene, Procollagen-Lysine, 2-Oxoglutarate 5-Dioxygenase 2 (PLOD2), which has a progressive and metastasizing function in cancer." (PMID 32455614, 2020). "Through MTT and Transwell invasion assays, we confirmed the pro-cancer abilities of PLOD1 and PLOD2, which provided new basis for the molecular mechanism of RCC tumorigenesis." (PMID 33287763, 2020). "A recent study showed a signature involving P4HA1, PLOD1, KDM3A, PLOD2, and ASPH predicted prognosis in various cancers including LUAD using bioinformatic analysis." (PMID 33299876, 2020). "M.SssI fusions induced de novo DNA methylation, changed histone modifications in a context-dependent manner, and led to 50%–70% reduction in PLOD2 expression in fibrotic fibroblasts and in MDA-MB-231 cancer cells." (PMID 32455614, 2020). "Of the 10 proteins, the preceding text showed that some studies identified RRM2, PLOD2, MKI67, MCM5, and CKD1 promoted cancer progression and FBP1, FBP2, ENO3, GPD1, and ASS1 inhibited cancer progression, which was consistent with our results." (PMID 33200655, 2020). "A number of studies have demonstrated that overexpression of PLOD2 and PLOD3 promotes cancer progression and metastasis." (PMID 31199049, 2019). "Many studies demonstrate that increased PLOD2 and PLOD3 expression is required for cancer progression and metastasis." (PMID 30003082, 2018).
cancer (continued). "Since the client protein and function of PLOD1, PLOD2, and PLOD3 in collagen synthesis are different, it is important to develop specific inhibitors for PLOD to halt cancer progression." (PMID 30003082, 2018). "We are the first to report that adipocyte-derived adipokines activate PLOD2 expression via activation of the JAK/STAT3 and PI3K/AKT signaling pathways, thus promoting cancer migration and metastasis." (PMID 30563531, 2018). "Moreover, PLOD2 knockout effectively blocked hypoxia-induced EMT activation, and prevented hypoxia from triggering cancer cell migration and invasion in transwell assays in both cell lines." (PMID 40775208, 2025). "Like PLOD2, PLOD1 is involved in collagen hydroxylation, and its upregulation in ICA suggests increased collagen synthesis, leading to a dense ECM, as demonstrated in other cancer types." (PMID 40034261, 2025). "PLOD1, PLOD2, and PLOD3 levels were upregulated in most cancers." (PMID 39068670, 2024). "In addition, leptin and adipocyte-derived IL-6 enhance the expression of lysyl hydroxylase (PLOD2) by activating the JAK/STAT3 and PI3K/AKT signaling pathways, ultimately facilitating cancer cell metastasis." (PMID 39192979, 2024). "Both PLOD2 and P4HA1 are enzymes involved in collagen-related pathways and proved to be a biomarker of epithelial-to-mesenchymal transition (EMT) in multiple types of cancers." (PMID 36901940, 2023). "Interestingly, IL-6 together with leptin can increase the expression of procollagen-lysin-2-oxoglutarate 5 dioxygenase (PLOD2), a protein involved in ECM remodeling, and therefore has a decisive role in cancer cell invasion and EMT." (PMID 35625629, 2022). "For example, collagen prolyl 4-hydroxylases (P4Hs), essential enzymes in the synthesis of collagens and collagen lysyl hydroxylases (PLOD2) required for ECM stiffness, are induced in cancer cells by exposure to hypoxia, which is dependent on HIF-1α, but not HIF-2α." (PMID 34202979, 2021). "The prognosis of PLOD2 has been reported in several human cancers before, but it has never been described in CESC." (PMID 34258263, 2021). "PLOD2 is significantly overexpressed in several malignant tumors but no studies have been performed on what the cell types express this protein." (PMID 34944486, 2021). "Also, immunohistochemical staining showed that overexpressed PLOD2 and PLOD3 were detected in cancer lesions." (PMID 31199049, 2019). "Due to the correlation between PLOD2 and CD44/CD133 expression, PLOD2 might contribute to increasing cancer cell-like characteristics in LSCC." (PMID 31455288, 2019). "Here, we infer that PLOD2 may promote the translation or activity of Wnt/β-catenin to maintain CSCs in LSCC and thus contribute to cancer cell drug resistance." (PMID 31455288, 2019). "Strikingly, PLOD2 expression increased in MDA-MB-231 and MDA-MB-468 cells following culturing of these cells in CM obtained from adipocytes and CM obtained from adipocytes previously grown in the presence of cancer cells." (PMID 30563531, 2018). "Moreover, we implicate several of these gene hits not only in ccRCC for the first time (BHLHB3, CAMK1, CDH13, ENPP3, KCNJ2, KSR1, PLOD2, and TCF8), but also in a cancer model for the first time (CEP290, EFCAB3, PGBD5, RAPGEF5, SSPN, and TOX2)." (PMID 24979721, 2014). "The functional importance of both DCLK1-L and PLOD2 in hypoxia-driven ccRCC malignance, along with the validated PLOD2-DCLK1-L cascade in hypoxia signaling, prompted us to further examine the contribution of DCLK1-L to PLOD2-driven cancer invasiveness and stemness." (PMID 40775208, 2025). "In addition, cancer cells migrate faster in CAAs-embedded collagen gel than in mature adipocytes embedded in collagen gel, and CAAs-derived collagen remodeling is regulated by the PAI-1/PLOD2 axis." (PMID 39125923, 2024). "Although a number of studies have been carried out on PLOD2, no single study exists which could overall evaluate its effects on considerable types of cancers." (PMID 35586565, 2022).
cancer (continued). "Previous studies showed silencing of PLOD2 led to the inhibition of migration and invasiveness of multiple cancer cells themselves, which might mediate by abrogating the epithelial-mesenchymal transition (EMT) of those cancer cells." (PMID 31170987, 2019).
connective tissue disorder (4 papers, 2017 to 2023). A disease involving the connective tissue. "Bruck syndrome 2 (BS2) refers to a connective tissue disorder that results from mutations in PLOD2 that interfere with the ability of LH2 to hydroxylate lysyl residues on the telopeptide." (PMID 37686358, 2023).
adenocarcinoma (2 papers, 2017). A common cancer characterized by the presence of malignant glandular cells. "The expression levels of both P-EGFR and PLOD2 were higher in adenocarcinoma tissues than that in normal tissues." (PMID 29072684, 2017). "Moreover, the coexpression analysis suggested that P-EGFR and PLOD2 were simultaneously expressed in adenocarcinoma tissues and tissue microarray, which were consistent with the results shown in NSCLC cell lines." (PMID 29072684, 2017).
bone disorder (2 papers, 2017 to 2023). "Eight AFF patients (NS2‐9) without a clinical suspicion of a monogenic bone disorder carried one or more heterozygous VUS with a CADD score ≥ 20 in P4HB, PHEX, TNFRSF11A, CREB3L1, TCIRG1, SERPINH1, LEPRE1, and PLOD2." (PMID 37076969, 2023).
infection (2 papers, 2020 to 2025). The state of being infected such as from the introduction of a foreign agent such as serum, vaccine, antigenic substance or organism. "In this disease model, PLOD2 protein production was strongly repressed at day-two post-infection when compared to the ZF without effector domain (NoED) and the empty vector (EV) controls." (PMID 32455614, 2020).
PLOD2 also shares sentences with these, for which no sentence is quoted: COVID-19 (4 papers); idiopathic pulmonary fibrosis (4); oral carcinoma (4); lung fibrosis (3); gastric adenocarcinoma (2); melanoma (2); ovarian carcinoma (2); scoliosis (2); arthrogryposis (1); Ataxia (1); atherosclerosis (1); basal cell carcinoma (1); bone tumor (1); breast (1); cardiovascular disease (1); Cerebral ischemia (1); Cirrhosis (1); endometrial adenocarcinoma (1); esophageal adenocarcinoma (1); hepatitis C (1); hypercoagulation (1); hypopharyngeal squamous cell carcinoma (1); Intellectual disability (1); Kyphoscoliosis (1); laryngeal squamous cell carcinoma (1); liver fibrosis (1); lung squamous cell carcinoma (1); metastasis (1); metastatic neoplasm (1); microcephaly (1).
A further 12 diseases each share a sentence with PLOD2 in 1 paper.